OR2H1 (olfactory receptor family 2 subfamily H member 1)
Description:
Odorant receptor.
Synonyms: OR6-2; OR2H6; OR2H8; 6M1-16; HS6M1-16; OLFR42A-9004-14; OLFR42A-9004.14/9026.2; dJ994E9.4
Tractability: Small molecule: it belongs to a druggable protein family. Antibody: UniProt places it where antibodies can reach, with medium confidence; UniProt predicts a signal peptide or a membrane-spanning region; its Gene Ontology location is reachable by antibodies, with medium confidence.
Gene: Protein-coding gene on chromosome 6 (29,457,155 to 29,464,328, forward strand). Ensembl gene ENSG00000204688.
Subcellular location: Cell membrane
Pathways (Reactome):
Sensory Perception: Expression and translocation of olfactory receptors
Gene Ontology:
Molecular function: olfactory receptor activity; G protein-coupled receptor activity
Biological process: detection of chemical stimulus involved in sensory perception of smell; G protein-coupled receptor signaling pathway
Cellular component: plasma membrane; membrane
Genetic constraint (gnomAD): Loss-of-function variants: 0 observed, 0.83 expected, observed/expected ratio (o/e) 0, 90% interval 0 to 1.77. That is too few expected variants to judge how well the gene tolerates losing a copy. Missense variants: 377 observed, 380.71 expected, observed/expected ratio (o/e) 0.99, 90% interval 0.91 to 1.08. Synonymous variants: 155 observed, 161.47 expected, observed/expected ratio (o/e) 0.96, 90% interval 0.84 to 1.1.
Homologues: Orthologues: chimpanzee OR2H1 (97% identical), pig OLF42-3 (84% identical), pig OLF42-1 (84% identical), rat Or2h1 (84% identical), rat Or2h2c (84% identical), mouse Or2h1 (84% identical), rat Or2h1b (82% identical), rat Or2h2 (82% identical), mouse Or2h2 (81% identical), mouse Or2h1b (80% identical), mouse Or2h2b (79% identical), mouse Or2h2c (79% identical), and 1 more. Paralogues in human: OR2H2 (85% identical), OR2G3 (59% identical), OR2C1 (57% identical), OR2B11 (55% identical), OR2W3 (55% identical), OR2G2 (54% identical), OR2J1 (54% identical), OR2J2 (54% identical), OR2J3 (54% identical), OR2B2 (53% identical), OR2G6 (53% identical), OR2C3 (53% identical), and 80 more.
Diseases named in the same sentence as OR2H1 in open-access papers:
OR2H1 is named in the same sentence as 2 diseases in open-access papers, as found by Europe PMC text mining. Sharing a sentence is not in itself a finding about the gene and the disease. The quoted sentences say what the papers report.
tumor (1 paper, 2024). "A study targeting the olfactory receptor OR2H1 with CAR T cells showed specific cytotoxic activity against tumor cells and inhibited tumor growth, providing significant insights into the potential of targeting less conventional antigens." (PMID 39335203, 2024).
OR2H1 also shares sentences with these, for which no sentence is quoted: rheumatoid arthritis (1 paper).